MCL1 (MCL1 apoptosis regulator, BCL2 family member)
Diseases named in the same sentence as MCL1 in open-access papers (continued):
Sharing a sentence is not in itself a finding about the gene and the disease.
tumor (continued). "Previously, we showed that combining Apo2L/TRAIL with sorafenib, a multikinase inhibitor, results in dramatic efficacy in Apo2L/TRAIL-resistant tumor xenografts via inhibition of Mcl-1." (PMID 24086526, 2013). "The prior studies suggest that reduction of Mcl-1 or induction of NOXA sensitized cells to chemotherapeutic drugs including ABT-737 in a variety of tumor models." (PMID 24223823, 2013). "To evaluate the ability of Minnelide to regulate Mcl-1 and miR-204 levels in a preclinical setting, we analyzed Mcl-1 and miR-204 expression in three patient tumor xenografts treated with Minnelide." (PMID 24025188, 2013). "The investigation of the function mechanism indicated that miR-26a inhibited the tumor growth by at least partially targeting MCL-1." (PMID 23750239, 2013). "REN cells, a Bcl-xL and Mcl-1 overexpressing tumor cell line, were exposed to vehicle control, ABT-737 and JY-1-106, respectively." (PMID 23680104, 2013). "Especially effective would be the inhibition of the Mcl-1, since the tumor states are overly abundant among the survival states involving the activity of Mcl-1." (PMID 23767791, 2013). "EIF4E is a key factor in cap-dependent translation initiation (including several important oncoproteins such as c-Myc, cyclin D1, hypoxia-inducible factor 1, and Mcl-1) that controls tumor cell growth and survival." (PMID 23383345, 2013). "For instance, an increased expression of Bcl-xL and Mcl-1 has been shown for CRCs and correlates with poor differentiation, higher tumor stage and poor prognosis of the patients." (PMID 24098503, 2013). "Bcl-xL has been shown to be involved in breast cancer metastasation and CRC migration, but the role of Bcl-2 and Mcl-1 to tumor spread remains unsolved." (PMID 24098503, 2013). "The apparent relationship between the activity of the Mcl-1 and tumor states suggests that inhibition of Mcl-1 can be of special therapeutic relevance of targeting tumor cells." (PMID 23767791, 2013). "Introduction of anti-Mcl1-siRN A into tumor cells enhances their sensitivity to chemotherapeuticagents that induce apoptosis." (PMID 24303201, 2013). "It is over-expressed in human tumor tissue and promotes cell survival, and shRNA-mediated knockdown of Mcl-1 triggers apoptosis in lymphoma cells." (PMID 24025188, 2013). "The correlation between ERK1/2 activation and Mcl-1 expression in tumor samples from patients with HGSOC suggest that the ERK1/2/Mcl-1 pathway likely exerts a protective anti-apoptotic effect to tumor cells and is biologically relevant." (PMID 23158473, 2012). "We have recently demonstrated that Hif-1alpha is stabilized in cells infected with C. trachomatis and induces the strong up-regulation of the tumor suppressor and apoptosis inhibitor Mcl-1." (PMID 23077614, 2012). "Blocking STAT3 protein in human tumor cells has been shown to down-regulate Mcl-1 expression and induce tumor cell apoptosis." (PMID 23166634, 2012). "STAT3 relevance in oncogenesis/tumor progression is widely acknowledged, via regulating apoptosis-related genes (Bcl-XL, Mcl-1 and Survivin), proliferation- (c-myc and cyclin D1) and invasion-promoting genes (VEGF, MMP-9)." (PMID 23028842, 2012). "In the xenograft model of the BRAF mutant cell line OCM1A, Western analysis of frozen tumor tissue revealed that cooperative MCL-1 downregulation and increased BIM levels were also achieved in vivo." (PMID 22808163, 2012). "Akt kinase, autophagy, and elevated Bcl-xL and Mcl-1 can cooperate to protect tumor cells against chemotherapy-induced apoptosis by maintaining mitochondrial stability." (PMID 23171055, 2012). "The downregulation of Mcl-1 or Bcl-xL via RNAi was found to increase the sensitivity of the tumor cells to chemotherapy." (PMID 23171055, 2012). "We additionally found that the USP9X inhibitor WP1130 promotes Mcl-1 degradation and increases tumor cell sensitivity to chemotherapies." (PMID 23171055, 2012).
tumor (continued). "Agents that induce Mcl-1 turnover, and inhibitors designed to target the protein, can promote tumor cell death." (PMID 23056582, 2012). "The relative expression of Mcl-1 in tumor cells can be regulated at the transcriptional level or through post translational modifications by ERK." (PMID 23158473, 2012). "It has also been reported that DMAG-17 can induce apoptosis in tumor cells through down-regulating IKKs, Mcl-1, and survivin expression." (PMID 21347335, 2011). "On the other side, malignant hepatocytes that over expresses Mcl-1 can be selected during tumor progression and eventually confer resistance of HCC cells to apoptosis triggers." (PMID 21504623, 2011). "Our studies for the first time provide firm experimental evidence for a potential role for the Fbw7 tumor suppressor in the modulation of the apoptotic pathway by governing Mcl-1 ubiquitination and destruction." (PMID 21608150, 2011). "Previous studies have shown that Mcl-1 is an anti-apoptotic protein that protects tumor cells against apoptosis." (PMID 22078414, 2011). "As ABT-737 leads to liver deterioration in Mcl-1 knockout mice, inhibition of Mcl-1 should be done in a tumor specific manner to induce apoptosis and tumor specific growth control." (PMID 21915275, 2011). "Sensitizing tumor cells to apoptosis induction by selectively targeting Mcl-1, in combination with conventional chemotherapy, has emerged as an attractive therapeutic strategy." (PMID 20085644, 2010). "Rapid turnover of Mcl-1 protein can be initiated by stress (such as serum withdrawal) through caspase-mediated and proteasome-dependent degradation in tumor cells." (PMID 20085644, 2010). "A number of studies have investigated this resistance to ABT-737 and have found consistently that Mcl-1 can indeed confer resistance to ABT-737 while experimental approaches that down-regulate Mcl-1 sensitize tumour cells to ABT-737." (PMID 20576107, 2010). "Mcl-1 knockdown also augmented tumor cell death after inhibition of the pro-survival PI3K/Akt pathway." (PMID 17014711, 2006). "Among the genes involved in the intrinsic route, those expressed at the highest level were Bax and Bcl-2L2 (bcl-w gene) in both low and high MKI tumours, immediately followed by survivin and Mcl-1." (PMID 16755292, 2006). "We have previously shown that Mcl-1 expression is considerably enhanced in human HCC tissue compared to adjacent non-tumor tissue." (PMID 17014711, 2006). "Tumour cells containing immunostaining for the antiapoptotic proteins Bcl-2 and Mcl-1 were present in 31% and 58% of the cases evaluated, respectively, whereas immunopositivity for the proapoptotic proteins Bax and Bak was found in 47% and 58% of the samples." (PMID 10070896, 1999). "Thus, Mcl1 functions as a context-dependent molecular switch via restraining malignant transformation during chronic inflammation while supporting tumor progression once neoplasia is established." (PMID 42194042, 2026). "The study revealed that the presence of anti-apoptotic proteins B-cell lymphoma 2 (Bcl-2) and Myeloid Cell Leukemia 1 (Mcl-1) is markedly upregulated in the tumor tissue of CRLM patients and correlates with a reduction in mitochondrial membrane potential (ΔΨm)." (PMID 41164182, 2025). "In ESCC tissue, amplification of genes such as WTIP and MCL1 (chromosome 19) may enhance tumor invasiveness and anti-apoptotic capacities, potentially influencing tumor progression and therapeutic response." (PMID 40963872, 2025). "Deletion of Sting1 in Mcl1Δhep mice reduces immune cell chemotaxis and tumor incidence." (PMID 41105787, 2025). "High MCL-1 expression was observed in 57% of tumor samples, with intermediate expression in 28%." (PMID 40612845, 2025). "For cohorts with emergent MCL-1 compensation in dynamic BH3 profiling, the cellular product can be upgraded to co-deliver NOXA (or granzyme B-NOXA fusions) or it can be combined with transient, tumor-confined MCL-1 antagonists while maintaining BCL-xL targeting." (PMID 41280927, 2025).
tumor (continued). "Tumor-specific BCL-XL or MCL1 inhibition may be achieved by novel targeting approaches using PROTACs or selective drug delivery strategies and would be transformational in many subtypes of malignancy." (PMID 40113751, 2025). "The addition of AMG 176 to sotorasib led to greater tumor response than sotorasib alone in LKB1-deficient PDX tumors with MCL-1-dependent priming but not LKB1-deficient PDX tumors." (PMID 40316540, 2025). "MCL1 is one of the most overexpressed proteins in several tumor entities." (PMID 41326406, 2025). "Immunotherapy: Immunotherapy may activate immune cells to identify and destroy tumor cells, with some mechanisms potentially involving the regulation of MCL1 expression in the apoptosis pathway." (PMID 40026415, 2025). "Interestingly, belinostat's anticancer activity was also enhanced by inhibitors of Bcl‐xL or Mcl‐1 in patient‐derived tumor organoids." (PMID 40483575, 2025). "Notably, multivariate Cox regression analysis confirmed that high MCL-1 expression was a significant independent prognostic factor, even after adjusting for tumor size and metastasis." (PMID 40380182, 2025). "Therefore, we assessed the impact of belinostat as a single agent or in combination with inhibitors of Bcl‐xL or Mcl‐1 in patient‐derived tumor organoid models." (PMID 40483575, 2025). "Overall, our study of patient-derived tumor models identified MCL1 as therapeutic target in CDS." (PMID 40841513, 2025). "Some medications might promote tumor cell apoptosis by inhibiting MCL1 expression or regulating its function." (PMID 40026415, 2025). "Host growth−factor–driven ERK phosphorylation and MCL1 upregulation support tumor cell survival in the lung, providing an additional downstream module to monitor in metastatic specimens and to correlate with immune infiltration patterns conditioned by MAPK signaling." (PMID 41383615, 2025). "We then detected the MCL1 protein levels in tumor tissue by Western blot." (PMID 41312772, 2025). "In totality, our data support the hypothesis that short-term inhibition of MCL1 with BRD-810 can induce apoptosis in tumor cells while maintaining an acceptable safety profile." (PMID 39179926, 2024). "Given the observed trend of increasing high MCL-1 expression with higher grades in this study and considering the similarity to Namita’s study where a limited number of high-grade tumor samples were available, further research with a larger sample size remains necessary." (PMID 39012900, 2024). "Taken together, these results suggest that prolonged exposure of MCL1-inhibitory agents are likely to cause on-target cardiac toxicity, calling for the need for a potent MCL1 inhibitor with sufficient exposure to induce tumor apoptosis, yet a sufficiently short half-life to spare cardiotoxicity." (PMID 39179926, 2024). "The below average expression of MCL1 suggests that this anti-apoptotic protein may play only a minor role in relapse of the embryonal tumours MBG3 and NB." (PMID 38942989, 2024). "Furthermore, comparison of BRAFV600E versus BRAFWT CRCs in these datasets revealed that MCL1 mRNA expression was also significantly higher in BRAFV600E tumours (blue)." (PMID 38429301, 2024). "Similarly, CM-272 showed potent antitumor effects when combined with proapoptotic agents (Bcl-2 inhibitor venetoclax, BCL-XL inhibitor A1331852, MCL-1 inhibitor S63845) in multiple tumor types." (PMID 39488528, 2024). "PD-L1 has an anti-tumour activity through inhibiting myeloid cell leukemia-1 (MCL1) expression." (PMID 38893244, 2024). "Both specimens showed unequivocal expression of MCL1 within metastatic tumor cells." (PMID 37676378, 2024). "Similarly, USP13 interacts with and stabilizes Mcl‐1, and its inhibition reduces Mcl‐1 levels, increasing the sensitivity of tumor cells to BH3 mimetic inhibitors." (PMID 39678489, 2024).
tumor (continued). "Moreover, the KSHV latency-associated nuclear antigen (LANA) sequesters the MCL1 E3 ubiquitin ligase FWB7, thereby stabilizing the MCL1 protein and promoting tumor cell survival." (PMID 39386614, 2024). "Indeed, we found that MLN0128 treatment effectively suppressed c-MYC/MCL1/RictorKOTsc2KO tumor growth, and it was more effective than the p70S6K/RPS6 inhibitor everolimus." (PMID 39325536, 2024). "Mice receiving T cells pre‐cultured with G‐CSF and/or GM‐CSF or Mcl‐1 antibody‐treated TCNs exhibited decreased tumor progression, demonstrating the critical role of neutrophils with delayed apoptosis in assisting tumor growth in vivo." (PMID 39447112, 2024). "In addition, PTBP1 modulates the stability of the myeloid cell leukemia 1 (MCL1) transcript and promotes the accumulation of MCL1 in the cytoplasm, which inhibits the apoptosis of tumor cells." (PMID 39366930, 2024). "As for Mcl-1, major roles have been described in the sustained growth and therapy resistance of different tumors, and several studies have indicated its activation in tumor cells, related to chromosomal amplification, increased mRNA, and protein expression." (PMID 38542429, 2024). "In addition, the tumor tissue sections were subjected to IHC analysis to detect the expression of cell proliferation molecule Ki67 and MCL-1." (PMID 38706892, 2024). "Although early metastases were shown to express the most MCL1 protein, we found that both early and later, established metastatic lesions were highly susceptible to MCL1 inhibition in a murine model of metastasis, confirming MCL1’s importance in metastatic tumor cell survival." (PMID 37676378, 2024). "We hypothesized that inhibiting MCL1 would potentiate the anti-tumor effect of these agents, creating a unique clinical opportunity to combine both agents for improved responses." (PMID 38371625, 2024). "Therefore, it is urgent to improve the targeted binding efficiency of NSC 260594 to mitochondria and reduce the potential off-target effects, thereby enhancing the anti-tumor activity of Mcl-1 inhibitors and reducing toxicity." (PMID 39372954, 2024). "Indeed, our experiments show a significant degree of heterogeneity in the ERK, ERK target gene, and MCL1 responses within tumor cell populations, both in vitro and in vivo." (PMID 37676378, 2024). "In addition, tumor stromal microenvironment can also provide resistance to the action of Mcl-1 inhibition." (PMID 39372954, 2024). "In the c-MYC/Mcl1 model, tumor nodules emerged from the liver around 3–4 weeks after HDTVi." (PMID 37040183, 2023). "MCL-1 is upregulated in senescent tumor cells and in cells that express low levels of BCL-2." (PMID 37601693, 2023). "Furthermore, detailed time-course studies revealed that the combination therapy considerably delayed the progression of c-MYC/Mcl1 tumor lesions." (PMID 37040183, 2023). "Alternatively, miR-29 serves as a tumor suppressor in cholangiocarcinoma by targeting myeloid leukemia 1 (MCL-1) and in acute myeloid leukemia by orchestrating DNA methyltransferases, thereby restoring the expression of tumor suppressor genes through DNA hypomethylation." (PMID 38002007, 2023). "However, the rapid degradation is often deregulated, leading to high Mcl-1 protein levels in tumor tissues." (PMID 37173959, 2023). "Mcl‐1 has been identified as a critical factor in tumor cell survival and resistance to therapy." (PMID 37970406, 2023). "AFP immunization synergizes with anti–PD-L1 to dramatically inhibit c-MYC/Mcl1 tumor progression." (PMID 37040183, 2023). "Notably, venetoclax combined with the MCL-1 BH3 mimetic S63845 induced tumor regression in patient-derived xenograft synovial sarcoma models." (PMID 37894324, 2023). "This approach can also be applied to other tumor types which are co-dependent on MCL-1 and BCL-XL." (PMID 36588105, 2023). "Interestingly, Mcl-1 is upregulated in senescent tumor cells, including those expressing low levels of Bcl-2." (PMID 37047342, 2023).
tumor (continued). "Downregulation of MCL-1 expression significantly induced apoptosis of tumor cells." (PMID 37538176, 2023). "Moreover, AsiC mixtures can be easily created from the assembly of individual AsiCs, and the combination of the four most effective EpCAM-AsiCs (targeting Upf2, Parp1, Cd47, and Mcl1) exerted a better tumor inhibition effect than the individual EpCAM-AsiCs." (PMID 36969696, 2023). "Notably, TRPV1 inhibition by AMG9810 robustly dampened EGFR or AKT phosphorylation and downregulated MCL1 expression in the tumor cells." (PMID 37165076, 2023). "Furthermore, the AFP vaccine effectively prevented c-MYC/Mcl1 HCC initiation when administered before tumor formation, while it was ineffective against full-blown c-MYC/Mcl1 tumors." (PMID 37040183, 2023). "The function of EpCAM-AsiCs in the process of cancer immunity was evaluated in genetically engineered mouse breast cancer models, which indicated that Upf2, Parp1, Cd47, and Mcl1 knockdown by EpCAM-AsiCs obviously inhibited tumor progression and promoted tumor-infiltrating immune cell functions." (PMID 36969696, 2023). "AZD8055 caused dose-dependent suppression of MCL-1 expression in tumor cells without any observable effect in normal cells." (PMID 36588105, 2023). "We speculated that P7 regulated MCL-1 through the Wnt/β-catenin pathway, thereby inhibiting apoptosis and promoting drug resistance of tumor cells." (PMID 37063257, 2023). "Furthermore, increased inhibition in tumour in vivo depicted that the LNP-GEM-Mcl-1-siRNA has better anti-tumour efficacy on comparing to individual administration of GEM or Mcl-1-siRNA alone, thus proving the synergistic effect of co-delivery." (PMID 36635659, 2023). "The data indicated that downregulation of Mcl-1 expression inhibited in vivo tumor growth." (PMID 37259388, 2023). "The survival of tumor cells depends on STAT3's ability to activate MCL-1." (PMID 36852795, 2023). "Depletion of the NCOA3-p300-NF-κB components or blockage of NCOA3 function with inhibitors (gossypol and bufalin) in ER-positive cells suppressed BCL2, BCL2A1, BCL2L2, and MCL1 expression, while also decreasing cell viability, colony formation, cell invasion, and tumor growth." (PMID 36853387, 2023). "This is possibly because tumor cells that most downregulated MCL-1 via inhibition of mTOR pathway (AZD8055) in combination with navitoclax have undergone apoptosis (high levels of cleaved PARP and cleaved caspase 3) resulting in removal of dead cells from the tumor by phagocytosis." (PMID 37210412, 2023). "Similarly, MM patients overexpressing USP9x, which leads to increased MCL-1 stability, were shown to have a poor prognosis and can promote tumor survival." (PMID 37601693, 2023). "Nevertheless, whether bevacizumab leads to tumor cell apoptosis through the downregulation of Mcl-1 secretion remains uncertain." (PMID 35997665, 2022). "BCL2, CDK4 and MCL1 were highly expressed in all tumours studied." (PMID 35249548, 2022). "Altogether, these data suggest that the majority of senescent tumor cells rely on Mcl-1 over-expression and that this cell population upregulates gene pathways that may contribute to tumor progression through different mechanisms." (PMID 35449130, 2022). "Furthermore, immunohistochemistry showed that the expression levels of BCL‐2 and MCL‐1, two major cell apoptosis‐related molecules, were decreased by vandetanib in K562 tumor tissues." (PMID 35689424, 2022).